BAIAP3 (BAI1 associated protein 3)
Description:
Functions in endosome to Golgi retrograde transport. In response to calcium influx, may interact with SNARE fusion receptors and membrane phospholipids to mediate endosome fusion with the trans-Golgi network. By promoting the recycling of secretory vesicle transmembrane proteins, it indirectly controls dense-core secretory vesicle biogenesis, maturation and their ability to mediate the constitutive and regulated secretion of neurotransmitters and hormones. May regulate behavior and food intake by controlling calcium-stimulated exocytosis of neurotransmitters including NPY and serotonin and hormones like insulin. Proposed to play a role in hypothalamic neuronal firing by modulating gamma-aminobutyric acid (GABA)ergic inhibitory neurotransmission (By similarity).
Synonyms: BAP3; KIAA0734
Tractability: Antibody: UniProt places it where antibodies can reach, with high confidence; its Gene Ontology location is reachable by antibodies, with high confidence.
Gene: Protein-coding gene on chromosome 16 (1,333,638 to 1,349,439, forward strand). Ensembl gene ENSG00000007516.
Subcellular location: Cytoplasm, cytosol; Recycling endosome membrane; Late endosome membrane; Golgi apparatus, trans-Golgi network membrane; Cell membrane
Gene Ontology:
Molecular function: calcium ion binding; phospholipid binding; protein binding; SNARE binding; syntaxin binding
Biological process: dense core granule maturation; G protein-coupled receptor signaling pathway; positive regulation of insulin secretion involved in cellular response to glucose stimulus; positive regulation of neurotransmitter secretion; regulation of dense core granule exocytosis; retrograde transport, endosome to Golgi; regulation of synaptic transmission, GABAergic; modulation of chemical synaptic transmission; regulation of behavior
Cellular component: cytosol; dense core granule; early endosome membrane; late endosome membrane; plasma membrane; recycling endosome membrane; trans-Golgi network membrane; secretory vesicle; GABA-ergic synapse; Golgi apparatus; presynapse
Genetic constraint (gnomAD): Loss-of-function variants: 181 observed, 145.67 expected, observed/expected ratio (o/e) 1.24, 90% interval 1.1 to 1.41. The synonymous counts are far from expectation, so gnomAD's model fits this gene poorly and the ratio says little. Missense variants: 1,765 observed, 1,516.8 expected, observed/expected ratio (o/e) 1.16, 90% interval 1.12 to 1.21. Synonymous variants: 844 observed, 647.25 expected, observed/expected ratio (o/e) 1.3, 90% interval 1.23 to 1.38.
Homologues: Orthologues: chimpanzee BAIAP3 (93% identical), mouse Baiap3 (89% identical), pig BAIAP3 (88% identical), rat Baiap3 (87% identical), guinea pig BAIAP3 (86% identical), tropical clawed frog baiap3 (55% identical), zebrafish baiap3 (49% identical), Drosophila melanogaster unc-13-4A (32% identical), Caenorhabditis elegans F54G2.1 (28% identical), Drosophila melanogaster stac (22% identical). Paralogues in human: UNC13D (32% identical).
Diseases named in the same sentence as BAIAP3 in open-access papers:
BAIAP3 is named in the same sentence as 16 diseases in open-access papers, as found by Europe PMC text mining. Sharing a sentence is not in itself a finding about the gene and the disease. The quoted sentences say what the papers report.
Anxiety (4 papers, 2017 to 2025). Intense feelings of nervousness, tension, or panic often arise in response to interpersonal stresses. "Moreover, at the behavioral level, loss of Cbln1 has been associated with impairments in fear memory and spatial learning, while loss of Baiap3 is implicated in the development of anxiety and depression." (PMID 40606839, 2025). "Baiap3 dysregulation has been associated with both major depressive disorder and AD, and it is regulated in a sex-dependent manner in mouse models and human subjects with anxiety, and also plays a role in the recovery from CNS injury." (PMID 39006222, 2024). "BAIAP3 was associated with anxiety and changes in response to benzodiazepines." (PMID 35431783, 2022). "BAIAP3 knockout mice display increased seizure propensity and anxiety behavior, which could result from abnormal neuropeptide or serotonin secretion." (PMID 28626000, 2017).
cervical adenocarcinoma (1 paper, 2021). An adenocarcinoma arising from the cervical epithelium. "We identified PIK3CA, NDN, GOLGA6L4, and BAIAP3 as SMGs in cervical adenocarcinoma and confirmed that NDN, GOLGA6L4, and BAIAP3 were novel SMGs." (PMID 33398034, 2021). "Fourth, in our study, after the evaluation of WES data in 20 cervical adenocarcinomas, six genes (i.e., PIK3CA, KRAS, TRAPPC12, NDN, GOLGA6L4, and BAIAP3) were predicted as driver genes that could promote tumor formation and development." (PMID 33398034, 2021).
leukoaraiosis (1 paper, 2021). "Given the enrichment of leukoaraiosis-associated microRNAs and mRNAs in neuron part and membrane system, BAIAP3 could potentially represent a novel target of hsa-miR-1972 in leukoaraiosis through which microRNAs are involved in the pathogenesis of white matter lesions." (PMID 33561007, 2021). "Among the microRNAs, hsa-miR-1972 was downregulated during the early onset phase of leukoaraiosis, as confirmed in independent patients, and it was found to target leukoaraiosis-dependent BAIAP3, decreasing its expression in 293T cell lines." (PMID 33561007, 2021).
Obesity (1 paper, 2017). Accumulation of substantial excess body fat. "A BAIAP3 missense mutation was detected in a search for hypothalamic signaling genes related to extreme obesity." (PMID 28626000, 2017).
ovarian tumors (1 paper, 2024). "Although there are no data on its role in ovarian tumors, its oncogenic meaning was demonstrated in desmoplastic small-round-cell tumor, an aggressive and rare cancer, in which the ectopic expression of BAIAP3 dramatically enhanced growth and colony formation in vitro." (PMID 39456618, 2024).
tumor (4 papers, 2012 to 2024). "BAIAP3 was also proposed to participate in growth factor secretion by tumor cells." (PMID 28626000, 2017). "BAIAP3, this protein is believed to participate in regulated exocytosis and expressed in tumour cells of DSRCT and enhance tumour growth by secretion of autocrine or paracrine growth factors." (PMID 22587803, 2012).
BAIAP3 also shares sentences with these, for which no sentence is quoted: cancer (2 papers); depression (2); age (1); amyotrophic lateral sclerosis (1); infection (1); memory impairment (1); neurodegenerative disease (1); ovarian carcinoma (1); retinitis pigmentosa (1); uveitis (1).